CLEC4C (C-type lectin domain family 4 member C)
Description:
Lectin-type cell surface receptor which may play a role in antigen capturing by dendritic cells. Specifically recognizes non-sialylated galactose-terminated biantennary glycans containing the trisaccharide epitope Gal(beta1-3/4)GlcNAc(beta1-2)Man. Binds to serum IgG. Efficiently targets ligand into antigen-processing and peptide-loading compartments for presentation to T-cells. May mediate potent inhibition of induction of IFN-alpha/beta expression in plasmacytoid dendritic cells. May act as a signaling receptor that activates protein-tyrosine kinases and mobilizes intracellular calcium.
Synonyms: BDCA-2; CD303; BDCA2; CLECSF11; CLECSF7; DLEC; HECL; PRO34150
Tractability: Antibody: a drug acting on it is in phase 2 or 3 trials; UniProt places it where antibodies can reach, with high confidence; its Gene Ontology location is reachable by antibodies, with high confidence; UniProt predicts a signal peptide or a membrane-spanning region.
Target class: Membrane receptor
Gene: Protein-coding gene on chromosome 12 (7,724,646 to 7,751,620, reverse strand). Ensembl gene ENSG00000198178.
Subcellular location: Cell membrane
Pathways (Reactome):
Immune System: Dectin-2 family; Neutrophil degranulation
Gene Ontology:
Molecular function: protein binding; carbohydrate binding; pattern recognition receptor activity
Biological process: antifungal innate immune response
Cellular component: plasma membrane; external side of plasma membrane; ficolin-1-rich granule membrane; secretory granule membrane; tertiary granule membrane
Genetic constraint (gnomAD): Loss-of-function variants: 8 observed, 17.15 expected, observed/expected ratio (o/e) 0.47, 90% interval 0.27 to 0.84. The upper end of that interval is the gene's LOEUF score, 0.84, which puts it in group 3 of 6, group 1 being the genes least tolerant of losing a copy. Missense variants: 158 observed, 174.96 expected, observed/expected ratio (o/e) 0.9, 90% interval 0.79 to 1.03. Synonymous variants: 58 observed, 56.74 expected, observed/expected ratio (o/e) 1.02, 90% interval 0.83 to 1.27.
Homologues: Orthologues: chimpanzee CLEC4C (99% identical), macaque CLEC4C (90% identical), mouse Clec4b1 (49% identical), mouse Clec4b2 (46% identical), rat Clec4b2 (46% identical), mouse Clec4a2 (43% identical), rat Clec4a (41% identical), rat Clec4a2 (41% identical), mouse Clec4a3 (41% identical), mouse Clec4a4 (41% identical), rat Clec4a3 (40% identical), zebrafish asgr1a (25% identical), and 16 more. Paralogues in human: CLEC6A (53% identical), CLEC4A (46% identical), CLEC4D (42% identical), CLEC4E (37% identical), CLEC4M (31% identical), CD209 (30% identical), CLEC10A (27% identical), ASGR2 (25% identical), CLEC17A (25% identical), CLEC4G (25% identical), ASGR1 (24% identical), CD207 (22% identical), and 2 more.
Diseases named in the same sentence as CLEC4C in open-access papers:
CLEC4C is named in the same sentence as 55 diseases in open-access papers, as found by Europe PMC text mining. Sharing a sentence is not in itself a finding about the gene and the disease. The quoted sentences say what the papers report.
viral infection (13 papers, 2010 to 2025). "pDC cells produce large amounts of IFNs in response to viral infection. pDC-specific markers CLEC4C (also known as BDCA-2), IL-3Rα (CD123), and CD2AP were highly expressed after MSC treatment." (PMID 34702946, 2021).
psoriasis (7 papers, 2007 to 2024). An autoimmune condition characterized by red, well-delineated plaques with silvery scales that are usually on the extensor surfaces and scalp. "CD123+ lymphoid cells in skin represent bona-fide pDCs35, as demonstrated by co-staining with BDCA2 (CLEC4C) in selected cryo-samples of paradoxical psoriasis." (PMID 29295985, 2018).
COVID-19 (5 papers, 2021 to 2024). A disease caused by infection with severe acute respiratory syndrome coronavirus 2. "CLEC4C is of interest as it is a factor linked to anti-viral responses and similarly, low clec4C expression has been linked to a particular COVID-19 severity-interaction expression quantitative trait loci." (PMID 36829233, 2023). "Among these proteins, KRT19, TOP2B, AREG, HGF, CKAP4, ITGB6, and NCF2 had a higher expression (> twofold) in plasma samples of severe compared to moderate COVID-19 patients, whereas CLEC4C and LTA were among the few proteins that were expressed at lower levels in severe patients." (PMID 36829233, 2023). "Finally, we evaluate the limited but non-zero effect of COVID-19 phenotype on eQTL discovery, and highlight the presence of COVID-19 severity-interaction eQTLs (ieQTLs; e.g., CLEC4C and MYBL2)." (PMID 35995775, 2022).
breast carcinoma (2 papers, 2020 to 2021). "Of these, three genes, POM121L2, KCNQ1, and CLEC4C, harbored significant methylation changes consistent with their differential expression in breast cancer." (PMID 33113958, 2020). "Of these, three genes, namely POM121L2, KCNQ1, and CLEC4C, harbored significant methylation changes consistent with their differential expression in breast cancer." (PMID 33113958, 2020).
liver cancer (1 paper, 2021). An epithelial or non-epithelial malignant neoplasm that arises from the liver. "The IHC results revealed no CLEC4A/G/J/K/M in normal and liver cancer tissues, whereas CLEC4C was highly expressed in HCC tissues, and CLEC4H1/H2 was lower expressed in HCC tissues compared to normal tissues." (PMID 34409028, 2021).
T lymphoma (1 paper, 2016). "In this study, we report that the deletion of a lysine residue at the extracellular region of CLEC4C yields a C-terminal dilysine motif that results in endoplasmic reticulum (ER) retention of the protein in transfected HeLa and Jurkat T lymphoma cell models." (PMID 26943047, 2016).
triple-negative breast carcinoma (1 paper, 2020). An invasive breast carcinoma which is negative for expression of estrogen receptor (ER), progesterone receptor (PR), and human epidermal growth factor receptor 2 (HER2). "CLEC4C codes for a lectin-type cell surface receptor that may play a role in antigen capturing by dendritic cells, inflammation, and immune response, and has been shown to be upregulated in triple negative breast cancer." (PMID 33113958, 2020).
tumor (26 papers, 2008 to 2025). "To validate the transcriptional data, we performed immunofluorescence microscopy on multiple advanced-stage MF samples staining for FPR2 and FCN1 to identify MF-specific tumor-associated macrophages (TAMs) and CLEC4C and LILRA4 to identify pDCs." (PMID 37669110, 2023).
infection (9 papers, 2011 to 2022). The state of being infected such as from the introduction of a foreign agent such as serum, vaccine, antigenic substance or organism. "In particular, pDC depletion induced in Clec4c+/DTR mice significantly impaired the host immune response to MVA infection." (PMID 32765505, 2020).
cancer (7 papers, 2018 to 2023). A tumor composed of atypical neoplastic, often pleomorphic cells that invade other tissues. "In smokers, CLEC4C, LILRA4, and TLR9 levels were consistently higher than those in non-smokers; however, statistical significance was not reached, probably because of the immense proportion of epithelial components, including cancer cells (data not shown)." (PMID 37435086, 2023).
CLEC4C also shares sentences with these, for which no sentence is quoted: systemic lupus erythematosus (9 papers); autoimmune disease (5); atherosclerosis (3); gastric cancer (3); hematologic malignancies (3); melanoma (3); HIV-1 infection (2); acute myeloid leukemia (1); AIDS (1); Allergy (1); atopic dermatitis (1); autoimmune hepatitis (1); Autoimmunity (1); bacterial infection (1); Blastic plasmacytoid dendritic cell neoplasm (1); chlamydia pneumonia (1); cholangiocarcinoma (1); colon cancer (1); colon tumor (1); cutaneous lupus erythematosus (1); dengue (1); endometriosis (1); Granuloma (1); Graves disease (1); head and neck squamous cell carcinoma (1); hepatitis B (1); HSV keratitis (1); intrahepatic cholangiocarcinoma (1); kidney disease (1); lung carcinoma (1).
A further 15 diseases each share a sentence with CLEC4C in 1 paper.